RHOD (ras homolog family member D)
Description:
Involved in endosome dynamics. May coordinate membrane transport with the function of the cytoskeleton. Involved in the internalization and trafficking of activated tyrosine kinase receptors such as PDGFRB. Participates in the reorganization of actin cytoskeleton; the function seems to involve WHAMM and includes regulation of filopodia formation and actin filament bundling. Can modulate the effect of DAPK3 in reorganization of actin cytoskeleton and focal adhesion dissolution.
Synonyms: RhoHP1; ARHD; Rho; RHOM
Tractability: Small molecule: a structure with a bound ligand is known. Antibody: UniProt places it where antibodies can reach, with high confidence; its Gene Ontology location is reachable by antibodies, with high confidence. PROTAC: ubiquitination databases record sites on it; its protein half-life has been measured.
Gene: Protein-coding gene on chromosome 11 (67,056,839 to 67,072,019, forward strand). Ensembl gene ENSG00000173156.
Subcellular location: Cell membrane; Early endosome
Pathways (Reactome):
Signal Transduction: RHO GTPases Activate Formins; RHOD GTPase cycle
Gene Ontology:
Molecular function: protein binding; GTPase activity; guanyl-nucleotide exchange factor activity; G protein activity; GTP binding; protein kinase binding
Biological process: actin filament bundle assembly; focal adhesion assembly; lamellipodium assembly; positive regulation of cell adhesion; positive regulation of cell migration; regulation of small GTPase mediated signal transduction; Rho protein signal transduction; actin filament organization; regulation of actin cytoskeleton organization; regulation of focal adhesion assembly; small GTPase-mediated signal transduction
Cellular component: early endosome; cytosol; endosome membrane; Golgi membrane; mitochondrial outer membrane; plasma membrane
Genetic constraint (gnomAD): Loss-of-function variants: 9 observed, 13.18 expected, observed/expected ratio (o/e) 0.68, 90% interval 0.41 to 1.19. The upper end of that interval is the gene's LOEUF score, 1.19, which puts it in group 5 of 6, group 1 being the genes least tolerant of losing a copy. Missense variants: 250 observed, 239.83 expected, observed/expected ratio (o/e) 1.04, 90% interval 0.94 to 1.16. Synonymous variants: 120 observed, 107.38 expected, observed/expected ratio (o/e) 1.12, 90% interval 0.96 to 1.3.
Homologues: Orthologues: chimpanzee RHOD (100% identical), macaque RHOD (99% identical), dog RHOD (87% identical), guinea pig RHOD (86% identical), pig RHOD (84% identical), mouse Rhod (83% identical), rat Rhod (63% identical). Paralogues in human: RHOF (50% identical), RHOA (47% identical), RHOB (46% identical), RHOC (46% identical), RAC3 (46% identical), RAC1 (45% identical), RAC2 (43% identical), CDC42 (41% identical), RHOG (40% identical), RHOQ (38% identical), RHOU (38% identical), RHOV (38% identical), and 10 more.
Diseases named in the same sentence as RHOD in open-access papers:
RHOD is named in the same sentence as 23 diseases in open-access papers, as found by Europe PMC text mining. Sharing a sentence is not in itself a finding about the gene and the disease. The quoted sentences say what the papers report.
breast carcinoma (4 papers, 2017 to 2025). "OVOL1 is highly expressed in ER + breast cancer, while RHOD has a causal role specifically in ER + breast cancer." (PMID 39720180, 2024). "We found robust evidence that RHOD expression may be causally and positively related to breast cancer risk, and that CDC42 may potentially be causally and negatively related to breast cancer risk." (PMID 35087170, 2022). "However, the evidence of colocalization was weak for ER− breast cancer risk and RHOD eQTLs (9%)." (PMID 35087170, 2022). "We repeated the same analyses above in the oestrogen receptor positive (ER+) subgroup, as our Mendelian Randomization results suggested a stronger relationship between RHOD and ER+ breast cancer." (PMID 35087170, 2022). "The power to detect the odds ratio of 1.2 (or equally 0.80) was > 99% for RHOD in overall, ER+ and ER− breast cancer using eQTL obtained from breast tissue and ≥ 30% using eQTL obtained from blood." (PMID 35087170, 2022). "Further analyses based on PAM50 subtype of breast cancer suggest that higher RHOD expression led to worse OS in more aggressive tumour subtypes (Luminal B, Her2 positive and Basal), but some results for RFS.were conflicting." (PMID 35087170, 2022). "Together, our results suggest that RHOD may play an important role in breast cancer aetiology and the mechanisms through which RHOD could drive breast cancer formation merit further investigation." (PMID 35087170, 2022). "Given that the activity of RHOD and CDC42 proteins is regulated by a variety of other proteins, it will be interesting to determine whether any of the genes encoding these regulators are also associated with breast cancer risk." (PMID 35087170, 2022). "Our results using publicly available datasets show a relatively low frequency of amplifications and copy number alterations within TGCA for RHOD and a prognostic role of RHOD in both RFS and OS of oestrogen receptor positive breast cancer." (PMID 35087170, 2022). "As we obtained only one SNP for the eQTL for RHOD from both breast tissue and blood, and none from breast cancer tissue, we were unable to perform multiple SNP sensitivity analyses." (PMID 35087170, 2022).
pituitary adenoma (3 papers, 2019 to 2023). "As for RHOD, ras homolog family member D, our study showed that RHOD expression is associated with short survival, which is partially in accord with a previous study that reported that the RHOD promotor was differentially methylated between pituitary adenoma and normal tissue." (PMID 36836422, 2023).
glioma (2 papers, 2015 to 2023). A benign or malignant brain and spinal cord tumor that arises from glial cells (astrocytes, oligodendrocytes, ependymal cells). "Inflammatory microglial cells, dendritic cells, myeloid cells, and glioma stem cells were highly expressed in GBM tissue, and ACP7, EPPK1, PCDHA8, RHOD, DRC1, ZIC3, and PRLR were significantly associated with survival." (PMID 36836422, 2023). "Seven Rho GTPases (RND1, RND3, RAC3, RHOA, RAC2, RAC1 and RHOC) showed a significantly greater connectivity in grade IV glioma and seven (CHP, RHOD, RHOF, RHOB, RHOQ, RND2, RHOBTB3) showed greater connectivity in grade II glioma." (PMID 26132659, 2015).
prostate carcinoma (2 papers, 2012 to 2025). A carcinoma that arises from epithelial cells of the prostate gland. "RhoD binds to the RBD domain of plexinB1 in the region where mutations are found in prostate cancer." (PMID 22404908, 2012).
acute myeloid leukemia (1 paper, 2021). Acute myeloid leukemia (AML) is a group of neoplasms arising from precursor cells committed to the myeloid cell-line differentiation. "Next, to determine the mRNA expression features of RhoF and RhoD in non-M3 AML patients, the RhoF and RhoD expression levels in TCGA datasets (Acute Myeloid Leukemia, NEJM 2013, n=157) 24 were compared, revealing a high RhoF expression level over that of RhoD." (PMID 34405015, 2021).
endometriosis (1 paper, 2025). The growth of functional endometrial tissue in anatomic sites outside the uterine body. "RHOD expression (codes for the GTPase RhoD) had a negative causal relationship with endometriosis, which aligns with previously published results that show that silencing RhoD leads to less efficient cell migration." (PMID 41377979, 2025).
esophageal squamous cell carcinoma (1 paper, 2024). Esophageal squamous cell carcinoma (ESCC) is a type of esophageal carcinoma (EC) that can affect any part of the esophagus, but is usually located in the upper or middle third. "CD44, TACSTD2, S100A14, and RHOD act as signatures to represent cancer‐spreading‐initiating cells in esophageal squamous cell carcinoma." (PMID 38864342, 2024).
Hematemesis (1 paper, 2022). The vomiting of blood. "Moreover, phenome-wide associated loci in the proximity of RHOD is a likely causal gene for cardiomegaly and hematemesis, the latter of which may explain the gastrointestinal bleeding observed in this patient." (PMID 36357925, 2022).
leukemia (1 paper, 2021). A malignant (clonal) hematologic disorder, involving hematopoietic stem cells and characterized by the presence of primitive or atypical myeloid or lymphoid cells in the bone marrow and the blood. "RhoF was highly expressed in hematological malignancies including lymphoma and AML, whereas RhoD was expressed at a low level in leukemia." (PMID 34405015, 2021).
lymph node metastasis (1 paper, 2024). "Multiplex immunohistochemistry (mIHC) staining of 4 MISs (CD44, S100A14, RHOD, and TACSTD2) in ESCC clinical samples demonstrated differential MIS expression scores (dMISs) predict lymph node metastasis, overall survival, and risk of carcinothrombosis." (PMID 38864342, 2024).
melanoma (1 paper, 2017). A malignant, usually aggressive tumor composed of atypical, neoplastic melanocytes. "RhoD was rarely expressed in melanoma cells, which was significantly lower than RhoD expression in MC." (PMID 28404912, 2017). "The RhoD transcription level of melanoma cells was significantly lower than that of MC." (PMID 28404912, 2017). "This indicates that RhoD can regulate the formation of stress fibers and adhesion plaque through DIAPH2, and influence the migration and invasion of melanoma cells." (PMID 28404912, 2017). "RhoD was highly expressed in MC, but was not expressed in melanoma cells." (PMID 28404912, 2017).
meningioma (1 paper, 2023). A generally slow growing tumor attached to the dura mater. "Interestingly, seven of the meningioma-associated antigens were shared between all WHO grades (NMA2, TBX15/18, XXLT1, SLC25A44, RHOD, CREBL2, and PLCD4)." (PMID 37368072, 2023).
myopia (1 paper, 2019). "We found over 3-fold hypermethylation of promoters of two Rho family genes, RHOD and RHOF, to be significantly associated with myopia." (PMID 30858441, 2019).
cancer (9 papers, 2021 to 2025). A tumor composed of atypical neoplastic, often pleomorphic cells that invade other tissues. "Additionally, some studies correlated RHOD expression to a higher BC risk, making it a very interesting target for cancer investigations." (PMID 40429857, 2025). "The combinations of these markers (MARCKSL1 + SLC9A3R1 + RHOD) when used together (ScreenCell cocktail) led to the staining of 100% of the cancer cells with the uppermost intensity." (PMID 40429857, 2025). "Again, no cancer-related point mutations have been reported for RHOD or RHOF, although they have both been shown to be differently expressed (mostly overexpressed) in cancer." (PMID 35454871, 2022). "These genes are involved in the regulation of cell cycle (CCND1, CDCA5, FOSL1, KDM2A, NUMA1, RHOD), apoptosis (FADD, ORAOV1), or the DNA damage response (DDB1, KAT/TIP60, MUS81, PACS1, RPS3), and several have been implicated in the HPV lifecycle and/or HPV-associated cancers." (PMID 40892869, 2025). "Using ScreenCell technology to isolate cancer cells spiked into normal blood, we tested the protein expression of all corresponding genes in vitro using the double immunocytochemistry method and validated MARCKSL1, SLC9A3R1, and RHOD as the most expressed markers." (PMID 40429857, 2025). "The signaling landscape that accompanies Ephexin3 in various cancer types included the tyrosine kinase receptor MET and the tyrosine phosphatase receptor PTPRF, the serine/threonine kinases MARK2 and PAK6, the Rho GTPases RHOD, RHOF and RAC1, and the cytoskeletal regulator DIAHP1." (PMID 38003617, 2023).
tumor (8 papers, 2012 to 2025). "RHOD plays a crucial role in the tumor invasion process by regulating fiber formation, cell movement, and other essential processes." (PMID 40141028, 2025). "Expression of the T1697A and T1795A mutant forms of plexinB1 in tumour cells is predicted to have the effect of releasing the cell from the inhibitory effect of RhoD on motility and stress fibre formation, thereby promoting motility." (PMID 22404908, 2012). "Interestingly, previous studies connected RHOD expression to tumorogenesis, higher tumor invasion capacity, and shorter survival." (PMID 40429857, 2025). "The co‐expression of any 1 gene from Group A (C19orf33, S100A14, and RHOD; count ≥1) and any 1 gene from Group B (CST6, CD44, TM4SF1, and TACSTD2; count ≥1) in a single tumor cell was defined as a MIC." (PMID 38864342, 2024). "Identification of EGF, RHOD, and GAP43 interaction central nodes suggests the disruption of the growth factor signaling, cytoskeletal dynamics, and neuronal differentiation, which could collectively impair tumor progression and metastasis." (PMID 41470892, 2025).
infection (1 paper, 2017). The state of being infected such as from the introduction of a foreign agent such as serum, vaccine, antigenic substance or organism. "Curiously, loss of RhoA, which promotes the spreading of ΔF11L-infected cells, was partially able to suppress the impact of the loss of RhoD during ΔF11L infection." (PMID 28486133, 2017).
RHOD also shares sentences with these, for which no sentence is quoted: hypopharyngeal cancer (1 paper); lung adenocarcinoma (1); lung carcinoma (1); lymphoma (1); pancreatic cancer (1); pituitary tumor (1); renal carcinoma (1).